MAGOH (mago homolog, exon junction complex subunit)
Description:
Required for pre-mRNA splicing as component of the spliceosome. Plays a redundant role with MAGOHB as core component of the exon junction complex (EJC) and in the nonsense-mediated decay (NMD) pathway. The EJC is a dynamic structure consisting of core proteins and several peripheral nuclear and cytoplasmic associated factors that join the complex only transiently either during EJC assembly or during subsequent mRNA metabolism. The EJC marks the position of the exon-exon junction in the mature mRNA for the gene expression machinery and the core components remain bound to spliced mRNAs throughout all stages of mRNA metabolism thereby influencing downstream processes including nuclear mRNA export, subcellular mRNA localization, translation efficiency and nonsense-mediated mRNA decay (NMD). The MAGOH-RBM8A heterodimer inhibits the ATPase activity of EIF4A3, thereby trapping the ATP-bound EJC core onto spliced mRNA in a stable conformation. The MAGOH-RBM8A heterodimer interacts with the EJC key regulator PYM1 leading to EJC disassembly in the cytoplasm and translation enhancement of EJC-bearing spliced mRNAs by recruiting them to the ribosomal 48S pre-initiation complex. Involved in the splicing modulation of BCL2L1/Bcl-X (and probably other apoptotic genes); specifically inhibits formation of proapoptotic isoforms such as Bcl-X(S); the function is different from the established EJC assembly.
Synonyms: MAGOHA; MAGOH1
Tractability: Small molecule: a structure with a bound ligand is known. PROTAC: ubiquitination databases record sites on it; its protein half-life has been measured.
Gene: Protein-coding gene on chromosome 1 (53,226,890 to 53,238,621, reverse strand). Ensembl gene ENSG00000162385.
Subcellular location: Nucleus; Nucleus speckle; Cytoplasm
Subcellular location (Human Protein Atlas): Nucleoplasm
Pathways (Reactome):
Metabolism of RNA: Nonsense Mediated Decay (NMD) enhanced by the Exon Junction Complex (EJC); Transport of Mature mRNA derived from an Intron-Containing Transcript; mRNA 3'-end processing; mRNA Splicing - Major Pathway
Developmental Biology: Regulation of expression of SLITs and ROBOs
Gene Ontology:
Molecular function: protein binding; RNA binding
Biological process: mRNA export from nucleus; mRNA metabolic process; nuclear-transcribed mRNA catabolic process, nonsense-mediated decay; regulation of alternative mRNA splicing, via spliceosome; regulation of mRNA processing; regulation of nuclear-transcribed mRNA catabolic process, nonsense-mediated decay; mRNA splicing, via spliceosome; RNA splicing
Cellular component: catalytic step 2 spliceosome; cytoplasm; exon-exon junction complex; exon-exon junction subcomplex mago-y14; nuclear speck; nucleoplasm; nucleus; post-spliceosomal complex; spliceosomal complex; U2-type catalytic step 1 spliceosome; U2-type catalytic step 2 spliceosome; cytosol
Genetic constraint (gnomAD): Loss-of-function variants: 0 observed, 9.68 expected, observed/expected ratio (o/e) 0, 90% interval 0 to 0.31. That is too few expected variants to judge how well the gene tolerates losing a copy. Missense variants: 36 observed, 109.53 expected, observed/expected ratio (o/e) 0.33, 90% interval 0.25 to 0.43. Synonymous variants: 27 observed, 40.33 expected, observed/expected ratio (o/e) 0.67, 90% interval 0.49 to 0.92.
Homologues: Orthologues: chimpanzee MAGOH (100% identical), guinea pig MAGOH (100% identical), mouse Magoh (100% identical), pig MAGOH (100% identical), rabbit MAGOH (100% identical), rat Magoh (99% identical), Drosophila melanogaster mago (90% identical), Caenorhabditis elegans mag-1 (80% identical). Paralogues in human: MAGOHB (99% identical).
Diseases named in the same sentence as MAGOH in open-access papers:
MAGOH is named in the same sentence as 18 diseases in open-access papers, as found by Europe PMC text mining. Sharing a sentence is not in itself a finding about the gene and the disease. The quoted sentences say what the papers report.
gastric cancer (4 papers, 2022 to 2024). A primary or metastatic malignant neoplasm involving the stomach. "High MAGOH expression has been interrelated with the malignant progression of multiple tumors, including gastric cancer, melanoma, and breast cancer, but its role in patients with LGG remains undiscovered." (PMID 37390121, 2023). "Previous studies have identified that e.g., in gastric cancer, a depletion of MAGOH or MAGOH and MAGOHB, next to inducing apoptosis, also significantly inhibited cell cycle progression." (PMID 36497117, 2022). "In gastric cancer, both MAGOH and MAGOHB have been identified to regulate key pathological processes such as cell proliferation and cell cycle progression." (PMID 36497117, 2022). "Interestingly, some upregulated genes found in RNA processing (MAGOH, SCAF11 and PLRG1) have been shown to play a role in tumorigenesis and cancer aggressiveness in glioma, liver, and gastric cancers." (PMID 36010871, 2022).
glioma (4 papers, 2022 to 2024). A benign or malignant brain and spinal cord tumor that arises from glial cells (astrocytes, oligodendrocytes, ependymal cells). "In gliomas, high levels of MAGOH/MAGOHB were associated with poor overall survival and worse response to treatments." (PMID 37294214, 2023). "High MAGOH/MAGOHB expression in grade 4 glioma seems to be particularly important, as loss of Chromosome 1p – where the MAGOH gene is located – is observed in some tumour types but rarely in grade 4 glioma." (PMID 37294214, 2023). "Increased MAGOH/MAGOHB expression was associated with poor prognosis in glioma patients, while knockdown of MAGOH/MAGOHB affected different cancer phenotypes." (PMID 37294214, 2023). "MAGOH/MAGOHB expression was also evaluated by immunostaining in an independent glioma cohort from the Shanghai ChangZheng Hospital." (PMID 37294214, 2023). "MAGOH/MAGOHB knockdown also affected viability of glioma stem cells (1919 and 3565)." (PMID 37294214, 2023). "Levels of MAGOH/MAGOHB expression were positively correlated with malignancy with 93.2% of grade 4 gliomas, 83.3% of grade 3 gliomas, but only 44.4% of grade 2 gliomas (p-value <0.001; displaying MAGOH/MAGOHB expression." (PMID 37294214, 2023). "The prognostic significance of MAGOH in LGG was analyzed in the TCGA and Chinese Glioma Genome Atlas (CGGA) cohorts." (PMID 37390121, 2023). "Next, we investigated MAGOH and MAGOHB expression in 674 glioma samples (grade 4 samples, n = 161; grade 3 samples, n = 267; and grade 2 samples, n = 246)." (PMID 37294214, 2023). "Moreover, 61% (72/118) of grade 4 gliomas showed highly positive staining for MAGOH/MAGOHB expression, significantly more than in grade 2 (29.6%) and grade 3 (41.17%) gliomas (p-value = 0.005)." (PMID 37294214, 2023).
melanoma (4 papers, 2021 to 2024). A malignant, usually aggressive tumor composed of atypical, neoplastic melanocytes. "It was further shown that MAGOH depletion in a melanoma cell line causes growth arrest." (PMID 36497117, 2022). "To achieve an efficient, simultaneous KD of both homologues and to gain a sufficient effect on cutaneous malignant melanoma cells, we designed a Pool of siRNAs targeting both MAGOH and MAGOHB." (PMID 36497117, 2022). "We observed an increased MAGOH/MAGOHB protein expression in most melanoma cell lines compared to healthy NHEM." (PMID 36497117, 2022). "These experiments additionally confirmed that the expression of MAGOH is vital for melanoma cell proliferation." (PMID 36497117, 2022). "Our findings demonstrate that cutaneous malignant melanoma cells rely on the expression of primarily MAGOH, but to an extent also MAGOHB, for their survival." (PMID 36497117, 2022). "However, the molecular mechanisms of MAGOH in melanoma pathogenesis as well as the importance of MAGOHB in this process has so far not been investigated." (PMID 36497117, 2022). "An siRNA-mediated knockdown of MAGOH significantly inhibits melanoma cell proliferation." (PMID 36497117, 2022). "MAGOH regulates melanoma production by controlling the proliferation of melanocyte." (PMID 33750478, 2021). "To analyze the protein expression of MAGOH and MAGOHB in melanoma, we performed Western blot experiments of several cutaneous melanoma cell lines as well as from normal human epidermal melanocytes (NHEM)." (PMID 36497117, 2022). "The experiment revealed that while a single KD of MAGOH increased the number of apoptotic cells when compared to the siCtrl, this effect was only statistically significant after a combined KD of MAGOH and MAGOHB for the melanoma cell lines Mel Ho and SKMel28." (PMID 36497117, 2022). "To further investigate MAGOH/MAGOHB expression at the protein level and its significance for melanoma development we performed immunohistochemical analysis of patient derived human tissue samples of primary or metastasis derived cutaneous malignant melanomas." (PMID 36497117, 2022). "A simultaneous inhibition of MAGOH and MAGOHB could be an approach to trigger melanoma cells to cell death, possibly enhance effects of other therapies and reduce cancer progression." (PMID 36497117, 2022). "This study aims to examine the expression of the homologues MAGOH and MAGOHB in melanocytes, several cutaneous melanoma cell lines and patient derived tissue samples and further elucidates the molecular function of both homologues in melanoma." (PMID 36497117, 2022). "Analyzing the occurrence of apoptosis showed that the KD of MAGOH and MAGOHB in melanoma cells using the siMAGOH/B Pool also significantly increased the proportion of apoptotic cells at a similar level compared to the simultaneous KD of MAGOH and MAGOHB with single siRNAs." (PMID 36497117, 2022). "Using functional assays, we could show that MAGOH, and not MAGOHB, is vital for melanoma cell growth, as an siRNA-mediated KD of only MAGOH significantly inhibits cell proliferation." (PMID 36497117, 2022). "This could mean that, compared to other cancer types, cutaneous melanoma exhibits an increased sensitivity to MAGOH (and MAGOHB) depletion with regards to apoptosis, meaning that cutaneous malignant melanoma cells undergo apoptosis before the cell cycle is affected." (PMID 36497117, 2022).
breast carcinoma (3 papers, 2017 to 2023). "Likewise, MAGOH has been shown to be differentially expressed in breast cancer, where it served, together with other RNA processing factors, to develop a robust stratification of breast cancer subtypes." (PMID 31561558, 2019).
glioblastoma (3 papers, 2020 to 2024). The most malignant astrocytic tumor (WHO grade IV). "We also observed changes in expression of four RNA processing regulators previously identified in genomic/functional screening for RNA binding proteins contributing to glioblastoma phenotypes: MAGOH, PPIH, ALYREF, and SNRPE70." (PMID 32488114, 2020). "Altogether, these results indicate that reduced expression of MAGOH/MAGOHB can create aberrant splicing events in glioblastoma cells, and suggest that high MAGOH/MAGOHB expression in tumours has an important role in preventing such events that are potentially harmful to tumour cells." (PMID 37294214, 2023). "We suggest that in these two scenarios (brain and glioblastoma development), highly proliferating cells demand efficient expression of cell cycle and division genes, and increased levels of MAGOH and MAGOHB are required to prevent defects in the splicing of these transcripts." (PMID 37294214, 2023). "High MAGOH/MAGOHB expression was observed in 14 tumour types; glioblastoma (GBM) showed the greatest difference compared to normal tissue." (PMID 37294214, 2023). "For example, the EJC proteins MAGOH and MAGOHB were among top hits identified in a functional genomic screening to identify RNA binding proteins with oncogenic potential in glioblastoma cells." (PMID 37294214, 2023).
microcephaly (3 papers, 2022 to 2024). A congenital or acquired developmental disorder in which the circumference of the head is smaller than normal for the person's age and sex. "The unstable MAGOH heterodimer complex is highly associated with microcephaly due to apoptosis." (PMID 36142288, 2022). "In mouse models, it was reported that haploinsufficiency of MAGOH, the other EJC core component, causes the defect of mitosis of neural stem cells, ending up in microcephaly." (PMID 39687031, 2024). "Conclusive evidence directly linking the EJC to early development came when MAGOH and RBM8A haploinsufficiency was shown to result in mouse microcephaly with follow up studies indicating high EJC enrichment in neural progenitors and the EJC being critical for cortical development." (PMID 35406756, 2022).
brain tumors (2 papers, 2023 to 2024). "We investigated the roles of two EJC members, the paralogs MAGOH and MAGOHB, with respect to brain tumour development." (PMID 37294214, 2023).
cutaneous malignant melanoma (2 papers, 2022 to 2024). "Thereby, the increased GADD45A expression observed after the loss of MAGOH/B could be efficiently downregulated in the cutaneous melanoma cell lines Mel Ho and 501Mel." (PMID 36497117, 2022). "In most cutaneous melanoma cell lines, the KD of MAGOH is also sufficient to significantly induce apoptosis, suggesting that the reduced proliferation is mainly caused by the occurrence of cell death." (PMID 36497117, 2022). "Our data indicate a critical role of MAGOH/MAGOHB expression for the tumor development of cutaneous malignant melanoma." (PMID 36497117, 2022). "This study revealed that cutaneous melanoma cells express significantly more MAGOH compared to MAGOHB on the mRNA as well as on the protein level." (PMID 36497117, 2022). "We identified that several cutaneous melanoma cell lines have an upregulated protein level of MAGOH and MAGOHB when compared to normal human epidermal melanocytes." (PMID 36497117, 2022). "In this study we could identify the NMD target GADD45A as strongly and significantly upregulated in cutaneous melanoma cells after KD of MAGOH and MAGOHB." (PMID 36497117, 2022). "Interestingly, in several other cutaneous melanoma cell lines, KD of only MAGOH was sufficient for inducing apoptosis, further indicating MAGOH as the more vital of the two homologues." (PMID 36497117, 2022). "Our study demonstrates that the KD of MAGOH and MAGOHB increased GADD45A expression in cutaneous melanoma, an effect that might be mediated by an impairment of NMD induced by the loss of MAGOH and MAGOHB." (PMID 36497117, 2022). "The previous results showed that a KD of MAGOH and MAGOHB dramatically induces apoptosis in cutaneous malignant melanoma cells." (PMID 36497117, 2022). "This study investigates the influence of MAGOH and its highly identical homologue MAGOHB with regards to cutaneous melanoma pathogenesis and cancer progression." (PMID 36497117, 2022). "In order to assess if MAGOH and MAGOHB influence NMD activity in cutaneous melanoma, their expression was knocked-down in Mel Ho and 501Mel using the siMAGOH/B Pool and the cells were subsequently transfected with a NMD reporter plasmid." (PMID 36497117, 2022). "As the KD of MAGOHB had proven to be efficient on the mRNA level, the absence of a KD of MAGOHB on the protein level supports the conclusion that MAGOH accounts for the majority of the total MAGOH and MAGOHB protein expression in cutaneous melanoma." (PMID 36497117, 2022). "This indicates a significant influence of MAGOH and MAGOHB on the expression of the pro-apoptotic NMD target GADD45A in cutaneous malignant melanoma." (PMID 36497117, 2022). "To analyze the role of MAGOH and MAGOHB expression for tumorigenesis of cutaneous malignant melanoma, we examined RNA-sequencing (RNA-seq) data from “The Cancer Genome Atlas” (TCGA) regarding MAGOH and MAGOHB mRNA expression in cutaneous melanoma patients." (PMID 36497117, 2022). "This study identifies high MAGOH and MAGOHB protein expression in cutaneous melanoma cell lines and patient derived tissue samples." (PMID 36497117, 2022). "The KD efficiency of the siPool on MAGOH and MAGOHB expression was confirmed in the cutaneous melanoma cell lines Mel Ho and 501Mel using qRT-PCR and Western blot analysis." (PMID 36497117, 2022). "In this study, we demonstrate that MAGOH and MAGOHB play an essential role in maintaining NMD activity in cutaneous melanoma." (PMID 36497117, 2022). "In this study, analyzing the influence of MAGOH and MAGOHB on cell proliferation and apoptosis, we observed additive effects after a simultaneous depletion of both homologues in cutaneous melanoma cells." (PMID 36497117, 2022). "Investigating the molecular mechanisms behind the observed cell death after KD of MAGOH and MAGOHB, we revealed a significant influence on the mechanism of NMD in cutaneous melanoma." (PMID 36497117, 2022).
cutaneous malignant melanoma (continued). "We further analyzed MAGOH and MAGOHB mRNA expression in different cutaneous melanoma cell lines derived from primary tumors (PT) or metastases (MET) using qRT-PCR and also observed a significantly higher expression of MAGOH compared to MAGOHB." (PMID 36497117, 2022). "A KD of MAGOH/MAGOHB and the resulting increase in GADD45A expression in cutaneous melanoma could possibly enhance the effect of other cancer therapies whose main mode of action is not to induce DNA damage, such as targeted therapy or immunotherapy." (PMID 36497117, 2022). "Together, the results revealed that cutaneous melanoma cells primarily rely on the expression of MAGOH, and not MAGOHB, for cell proliferation." (PMID 36497117, 2022). "In addition, it was further shown that a simultaneous downregulation of GADD45A together with MAGOH and MAGOHB could attenuate cell death in cutaneous melanoma cells, indicating GADD45A a strong tumor suppressor in cutaneous malignant melanoma." (PMID 36497117, 2022). "Hence, the inhibition of MAGOH and MAGOHB could constitute a promising new approach for the treatment of cutaneous melanoma." (PMID 36497117, 2022). "The experiment showed that a KD of MAGOH/B did not lead to a shift to neither more exon skipping nor more exon inclusion in Mel Ho or 501Mel indicating that MAGOH and MAGOHB do not influence this kind of exon skipping in cutaneous melanoma." (PMID 36497117, 2022). "After KD of MAGOH and MAGOHB using the siMAGOH/B Pool, a significant increase in GADD45A mRNA expression was observed in the cutaneous melanoma cell lines Mel Ho and 501Mel, whereas no obvious changes in the expression of GADD45B or GADD45G could be detected." (PMID 36497117, 2022).
ACTHomas (1 paper, 2019). "In this sense, in our cohort of ACTHomas, lower levels of MAGOH were found in men, who showed more chiasmatic compression, while higher MAGOH expression levels were associated with higher curation rate." (PMID 31561558, 2019). "In ACTHomas, our results demonstrated that the altered expression of only two SFs, MAGOH and KHDRBS1, was sufficient to fully discriminate ACTHomas from NPs." (PMID 31561558, 2019). "Indeed, these two SFs (MAGOH and KHDRBS1) were markedly overexpressed in ACTHomas, and ROC curves of these SFs corroborated their capacity to discriminate between ACTHomas and NPs with an AUC of 1 and 0.97, respectively (p < 0.0001)." (PMID 31561558, 2019).
gastric tumor (1 paper, 2024). "We also assessed the expression of MAGOH in 18 randomly selected GC tissues by western blotting, and the results confirmed that MAGOH was highly expressed in gastric tumor tissues." (PMID 38268030, 2024).
non-small cell lung carcinoma (1 paper, 2023). A group of at least three distinct histological types of lung cancer, including non-small cell squamous cell carcinoma, adenocarcinoma, and large cell carcinoma. "To build on the specificity and relevance of MAGOH/MAGOHB impact on splicing, we analysed another dataset in which MAGOH/MAGOHB expression levels were modulated in ChagoK1, a cell line derived from a non-small cell lung cancer that contains an hemizygous MAGOH-deletion." (PMID 37294214, 2023).